USP22 (ubiquitin specific peptidase 22)
Diseases named in the same sentence as USP22 in open-access papers (continued):
Sharing a sentence is not in itself a finding about the gene and the disease.
osteosarcoma (continued). "Mechanistically, USP22 regulates HK2 by deubiquitinating and stabilising β‐catenin expression, thereby promoting glycolysis in osteosarcoma cells." (PMID 39661501, 2024). "Molecules such as UBE2T, E3 ubiquitin ligase adaptor SPOP, USP9X, USP22, and BAP1 are involved in regulating the proliferation, migration, and invasion of osteosarcoma cells through modulation of the PI3K/Akt signaling pathway." (PMID 39062505, 2024). "In the present study, USP22 knockdown markedly reduced the protein levels of HK2 and β‐catenin and strongly suppressed the proliferation and glycolytic rate of osteosarcoma cells." (PMID 39661501, 2024). "In addition, USP22 knockout reduced the protein expression of β‐catenin and hexokinase 2 (HK2) in osteosarcoma cells." (PMID 39661501, 2024). "ALKBH5 upregulates the expression of USP22 and RNF40 by regulating the m6A levels of histones, leading to inhibition of H2A monoubiquitination and induction of critical oncogenes, ultimately promoting osteosarcoma progression." (PMID 39062505, 2024). "Moreover, USP22 downregulation repressed cell proliferation, invasion and epithelial-mesenchymal transition (EMT) via inactivation of PI3K/Akt signaling pathway in osteosarcoma cells." (PMID 35692754, 2022). "Additionally, treatment with the proteasome inhibitor MG132 restored β‐catenin protein levels in osteosarcoma cells regardless of the USP22 expression level." (PMID 39661501, 2024).
viral infection (7 papers, 2012 to 2025). "In the current study, we investigated the role of Usp22 deficiency in acute viral infection with lymphocytic choriomeningitis virus (LCMV)." (PMID 37896966, 2023). "Therefore, we expected that Usp22 deficiency in our mouse model of acute viral infection might improve the viral clearance in relation to the enforced interferon production." (PMID 37896966, 2023). "Collectively, these findings suggest that the enhanced immunity of virus-specific CD8+ T cells accompanied by the reduction of PD-L1 expression on antigen-presenting cells might have promoted liver immunopathology after acute viral infection with LCMV in Usp22 deficient animals." (PMID 37896966, 2023). "Mechanistically, viral infection strengthens the cooperation of Usp22 with another deubiquitinase Usp13 that promotes cleavage of the stimulator of interferon genes protein (STRING)." (PMID 37896966, 2023). "Until now, USP22-mediated STING ubiquitination has only been described upon viral infection and upon ectopic overexpression." (PMID 35933402, 2022). "Our findings elucidate USP22 as crucial host factor in shaping SARS-CoV-2 antiviral defense by priming cellular anti-viral responsiveness prior to viral infection." (PMID 35933402, 2022). "Interestingly, USP22 has mostly been associated with IFN signaling and ISG expression upon viral infection." (PMID 35933402, 2022). "Mitogen activation or virus infection in normal T and B lymphocytes may stimulate USP22 expression to promote cell immortalization, suggesting that the regulation of USP22 gene expression occurs mainly at the transcriptional level." (PMID 23300749, 2012). "In human intestinal epithelial cells, USP22 has been identified as a critical regulator of type III IFN signaling, acting through STING pathway activation to protect against viral infections." (PMID 40072090, 2025). "The results of previous in vitro studies support this presumption by demonstrating the negative regulator functions of Usp22 in type I and III interferon-mediated pathways after viral infection." (PMID 37896966, 2023). "Apart from studying USP22 functions on IFN signaling in mouse models, previous works exclusively investigated cellular functions of USP22 upon viral infection and applied overexpression models to analyze USP22 interactions and USP22-mediated ubiquitination." (PMID 35933402, 2022). "In light of our results, we also suggest that a viral infection with LCMV seems to be another potential trigger of granulocyte activation in the absence of Usp22." (PMID 37896966, 2023). "We identify USP22 as negative regulator of type III IFN secretion in basal settings without the addition of exogenous IFNs or by viral infection." (PMID 35933402, 2022). "Our findings reveal that USP22 regulates both basal and 2’3’-cGAMP-induced STING ubiquitination and activation, even in the absence of ectopic IFNs or viral infection, and loss of STING expression reverses the effects of USP22 KO on IFN signaling." (PMID 35933402, 2022). "We furthermore demonstrate for the first time that in the absence of viral infections or exogenous IFN, loss of USP22 expression resulted in basal and 2’3’-cGAMP-induced STING ubiquitination in hIECs." (PMID 35933402, 2022). "USP22 controls nuclear accumulation of IRF3 and type I IFN signaling through KPNA2 deubiquitination only upon infection with SeV and HSV-1 and loss of USP22 expression decreased type I IFN responses upon virus infection, while USP22 deletion in uninfected cells did not trigger basal IFN signaling." (PMID 35933402, 2022). "USP22-deficient hIECs strongly upregulate genes involved in IFN signaling and viral defense, including numerous IFN-stimulated genes (ISGs), with increased secretion of IFN-λ and enhanced STAT1 signaling, even in the absence of exogenous IFNs or viral infection." (PMID 35933402, 2022).
viral infection (continued). "Our study is the first to identify USP22 as a negative regulator of basal ISG expression, JAK/STAT activation, and IFN signaling, even in the absence of exogenous IFNs or viral infection." (PMID 35933402, 2022).
bladder cancer (6 papers, 2014 to 2026). "Another study also revealed that USP22 depletion reduced cell cycle progression and retarded tumor growth in animal models of bladder cancer, liver cancer, lung cancer, breast cancer and ovarian cancer." (PMID 37215134, 2023). "In bladder cancer, silencing USP22 by siRNAs induced cell cycle arrest and attenuated cell proliferation." (PMID 37215134, 2023). "Depletion of USP22 expression retarded the tumor growth of implanted bladder cancer cells in mice." (PMID 37215134, 2023). "Silencing of USP22 promoted the degradation of MDM2 in bladder cancer cells." (PMID 37215134, 2023).
lymph node metastasis (6 papers, 2012 to 2022). "In conclusion, our study provides evidence that USP22 expression is associated with histological subtype, lymph node metastasis, grade, Ki-67 and SOX2 expression in SACC patients, and also is an independent prognostic factor for SACC." (PMID 24466336, 2014). "In our meta-analysis, our results suggested that USP22 expression was correlated with lymph node metastasis, distant metastasis and the tumor TNM stage of GC patients." (PMID 35784926, 2022). "Other researchers have also detected the expression of USP22 in GC samples, and the results showed that USP22 protein expression levels are obviously upregulated in GC patients with lymph node metastasis." (PMID 35784926, 2022). "High expression of USP22 was significantly correlated with histological subtype, lymph node metastasis, grade, Ki-67 and SOX2 expression." (PMID 24466336, 2014). "In multivariate analysis, only lymph node metastasis and USP22 expression were the independent prognostic factors for OS and DFS in SACC." (PMID 24466336, 2014). "In summary, we reported that USP22 activated in a majority of clinical samples of OSCC and increased of USP22 expression exhibited a marked propensity toward highly malignant clinical behavior, lymph node metastasis, and poor survival after surgery." (PMID 22880026, 2012). "However, the correlation between USP22 expression and lymph node metastasis of GC patients is still contradictory." (PMID 35784926, 2022). "However, the expression of USP22 was correlated with lymph node metastasis (OR = 2.415, 95% CI, 1.082, P = 0.031), distant metastasis (OR = 3.956, 95% CI, 1.365–11.464, P = 0.011) and TNM stage (OR = 2.973, 95% CI, 1.153–7.666, P = 0.024)." (PMID 35784926, 2022). "High USP22 level was positively associated with large tumor size, extracapsular invasion, lymph node metastasis, distant metastasis, and TNM stage, but not significantly related with gender and age." (PMID 27145278, 2016). "The results showed that USP22 expression was correlated with histological subtype, lymph node metastasis, grade, Ki-67 and SOX2 expression, and the status of USP22 expression could be predictive factors of SACC." (PMID 24466336, 2014). "Moreover, statistical analysis showed that positive USP22 expression was positively related to lymph node metastasis, Ki67, Cox-2 and recurrence." (PMID 22880026, 2012). "Multivariate analyses showed lymph node metastasis (P = 0.041 for OS; P = 0.045 for DFS), Ki-67 expression (P = 0.005 for OS; P = 0.008 for DFS), as well as USP22 expression (P = 0.043 for OS; P = 0.047 for DFS) were associated with poor OS and DFS." (PMID 24466336, 2014). "In this meta-analysis, we reported that USP22 expression was closely related to lymph node metastasis, distant metastasis and TNM stage in GC patients but not to age, gender, depth of invasion, tumor differentiation and tumor size." (PMID 35784926, 2022). "Our correlation analysis based on high IHC scores showed that USP22 was significantly upregulated in CCA (p < 0.05), mainly in patients with a larger tumour, microvascular invasion and lymph node metastasis during a complete 57-month follow-up with the median period of 16.7 months." (PMID 34226501, 2021).
ovarian carcinoma (6 papers, 2017 to 2024). A malignant neoplasm originating from the surface ovarian epithelium. "Conversely, USP22 overexpression is associated with poor patient outcomes in multiple cancer types, including colorectal, pancreatic, breast, and epithelial ovarian cancers." (PMID 30781493, 2019). "For example, at the mRNA level in ovarian cancer, USP22 is downregulated in 20% of cases and upregulated in 2.5%; while collectively, at least one DUBm gene (USP22, ATXN7L3, ATXN7 or ENY2) is either downregulated in 47% of cases, or upregulated in 21% of cases (RNA-sequencing TCGA data)." (PMID 29210986, 2017). "Furthermore, ubiquitin specific protease 22 (USP22), high levels of which are associated with EOC and poor prognosis, have been shown to regulate the cell cycle pathway downstream of TGFβ1, consequently stimulating ovarian cancer cell proliferation." (PMID 28758950, 2017). "The identification of this positive feedback loop involving SRSF9, USP22, and ZEB1 offers new insights into the molecular mechanisms driving ovarian cancer progression." (PMID 39530604, 2024).
pancreatic ductal adenocarcinoma (6 papers, 2017 to 2025). An infiltrating adenocarcinoma that arises from the epithelial cells of the pancreas. "USP22 was also been reported to accelerate the development of cancer cells by targeting the DYRK1A in pancreatic ductal adenocarcinoma." (PMID 34753387, 2021). "Higher levels of autophagy are also observed in pancreatic ductal adenocarcinoma tissues where USP22 is reportedly overexpressed relative to normal tissues." (PMID 29210986, 2017). "Similarly, in pancreatic ductal adenocarcinoma cells, USP22 promotes the G1/S transition and proliferation by upregulating the expression of FoxM1, a key regulator of the G1/S and G2/M cell cycle transitions." (PMID 32063746, 2020). "In pancreatic ductal adenocarcinoma, strong USP22 IHC labeling was more prevalent in primary cancer tissues than normal tissues and was associated with shorter overall patient survival than weak or absent USP22 labeling." (PMID 29210986, 2017). "In pancreatic ductal adenocarcinoma (PDAC) cells, USP22 stimulated cell growth via targeting dual-specificity tyrosine regulated kinase 1A (DYRK1A)." (PMID 35692754, 2022).
gastric tumor (5 papers, 2017 to 2022). "In gastric tumors, USP22 expression was found to be positively correlated with the expression of the three well-known oncoproteins BMI1, c-Myc, and HSP90, which better predicted GC progression and prognosis than other methods." (PMID 36497313, 2022).
glioblastoma (5 papers, 2018 to 2024). The most malignant astrocytic tumor (WHO grade IV). "Noteworthy, the ortholog of the yeast Ubp8 and cancer signature gene Usp22 is a hallmark of aggressive glioblastoma tumors." (PMID 35626719, 2022). "Strikingly, our results prompted us to analyze glioblastoma tumor tissues where Usp22 has been reported to be a cancer signature linked to tumor prognosis." (PMID 35626719, 2022). "We believe that this model may represent a first attempt for future research to uncover the mechanism and metabolic processes involved in glioblastoma and mitochondria functions linked to the cancer gene Usp22." (PMID 35626719, 2022). "Sections from 30 different glioblastomas were immunostained with anti Usp22 and the reactivity evaluated as a sum between staining intensity and percentage of positive cells." (PMID 35626719, 2022). "Starting from these findings and previously published data, we extended our analysis to the human ortholog Usp22, one of the signature molecules of aggressive glioblastoma." (PMID 35626719, 2022). "Further, USP22 is shown to facilitate cell-cycle progression and colorectal tumorigenesis by targeting CCNB1 while in glioblastoma, USP22 promotes tumorigenesis via stabilizing KDM1A." (PMID 33805973, 2021). "This leads to KDM1A deubiquitination by ubiquitin-specific protease 22 (USP22) and subsequent stabilization, which is essential for glioblastoma development." (PMID 29793495, 2018). "Importantly, the protein levels of USP22, GSK3β, and LSD1 were found to be positively correlated with one another and concurrently increased in the nuclei of glioblastoma and glioma stem cells (GSCs)." (PMID 39394462, 2024).
acute myeloid leukemia (4 papers, 2017 to 2024). Acute myeloid leukemia (AML) is a group of neoplasms arising from precursor cells committed to the myeloid cell-line differentiation. "USP22 deficiency in Ras-driven myeloproliferative neoplasm blocks myeloid differentiation promoting acute myeloid leukemia." (PMID 38382674, 2024). "The specific mechanism of action is that the deletion of USP22 results in reduced levels of PU.1 under Kras mutation-driven MPN conditions, whereas previous studies have shown that reduced PU.1 expression and activity is common in mouse and human acute myeloid leukemia (AML) cases." (PMID 35935969, 2022). "USP22 can deubiquitinate Sirt1 and enhance its stability through c-MYC-related network, leading to FLT3 tyrosine kinase inhibitors (TKIs) resistance in acute myeloid leukemia (AML)." (PMID 28567015, 2017).
colitis (4 papers, 2021 to 2025). Inflammation of the colon. "USP22-deficient mice in a DSS-induced colitis model display increased local immune cell infiltration and higher serum IL-6 levels." (PMID 35145062, 2022). "Together, these findings demonstrate that the loss of Usp22 in a mouse model for colitis significantly elevates inflammation-associated signs." (PMID 33920268, 2021). "Together, our results suggest that USP22 suppresses Sparc expression in acute colitis and inflammation-associated CRC." (PMID 33920268, 2021). "In this study, we sought to investigate the consequences of an intestine-specific Usp22 deletion in mice undergoing acute dextran sodium sulfate (DSS)-induced colitis as well as inflammation-associated CRC." (PMID 33920268, 2021). "We evaluated the effects of a conditional, intestine-specific knockout of Usp22 during dextran sodium sulfate (DSS)-induced colitis and in a model for inflammation-associated CRC." (PMID 33920268, 2021). "Interestingly, Usp22-deleted mice displayed symptoms associated with colitis such as weight loss, presence of occult blood, diarrhea and epithelial damage." (PMID 33920268, 2021). "Indeed, mice with an intestine-specific loss of Usp22 displayed more severe colitis compared to wild type controls." (PMID 33920268, 2021). "In addition, these animals had significantly shortened colons, supporting the hypothesis that the loss of Usp22 elevates colitis severity." (PMID 33920268, 2021). "Subsequently, specific knockout UPS22 in IECs increased the severity of inflammation in mice with DSS colitis and promoted colitis-related colorectal cancer, further confirming the role of USP22 in repressing intestinal inflammation and tumors." (PMID 34956195, 2021). "In agreement with our previous observations, the intestinal deletion of Usp22 significantly elevated the disease activity index as well as the degree of epithelial damage in DSS-mediated colitis." (PMID 33920268, 2021). "Consistently, USP22 mRNA levels were decreased in ulcerative colitis (UC) patients displaying neoplasm (UCneo) compared to patients with colitis alone." (PMID 33920268, 2021). "Using a transcriptome-wide approach, we identified SPARC as the most highly upregulated gene following USP22 depletion and confirmed these findings in Usp22fl/fl mice experiencing acute colitis and CRC." (PMID 33920268, 2021). "Thus, we sought to test the consequences of an intestinal Usp22 deletion in acute dextran sodium sulfate (DSS)-induced colitis." (PMID 33920268, 2021). "Together, USP22 deficiency induced the upregulation of SPARC via affecting H3K27ac and H2Bub1 occupancy in human CRC cells and elevated SPARC levels in the colons of mice experiencing colitis and inflammation-associated CRC." (PMID 33920268, 2021). "Together, our findings uncover that USP22 controls SPARC expression and inflammation intensity in colitis and CRC." (PMID 33920268, 2021). "Interestingly, these results mechanistically connect USP22-mediated repression of SPARC expression via H2Bub1 deubiquitination, thereby possibly preventing the pro-inflammatory effect of SPARC in DSS-mediated colitis in mice." (PMID 33920268, 2021).